INS (insulin)
Diseases named in the same sentence as INS in open-access papers (continued):
Sharing a sentence is not in itself a finding about the gene and the disease.
infection (continued). "However, due to the change in insulin sensitivity, the action of insulin is reduced (φ is affected by infection incidence), and the patient is expected to deliver more insulin injections to counterbalance the effect of insulin resistance." (PMID 32784178, 2020). "Moreover, insulin also increase the adhesion and hence migration of PMNs to the site of infection through upregulation of ICAM-1 in endothelium cells." (PMID 32915806, 2020). "It allows a broad field of glucose and insulin dependent studies of infection." (PMID 33520591, 2020). "Upon infection, there was an increased viral titre in the cell culture supernatant and a marked reduction in glucose-stimulated insulin secretion (112.9 ± 24.4 vs 209.8 ± 24.4 ng [mg protein]–1 h–1; p = 0.006), compared with uninfected controls, but cellular viability remained unaffected." (PMID 32676816, 2020). "Reduced or impaired immunological responses, which render patients more susceptible to infections, have been observed in T1D, and this dysfunction is often related to a lack of insulin in the blood." (PMID 33312173, 2020). "Therefore, the availability of glucose in the circulation during infection is of crucial importance; this is achieved by the development of insulin resistance, an evolutionarily preserved response that allows the host to survive." (PMID 32708504, 2020). "The presence of elevated blood glucose levels despite injecting higher amounts of insulin and consumption of less carbohydrates is regarded as a marker of an event of infection incidence and hence can be defined as a microevent for the event-based digital infectious disease detection system." (PMID 32784178, 2020). "The evidence suggests that insulin may exert an anti-inflammatory effect by modulating the inflammatory response, and finally improves the symptoms of infection." (PMID 33679687, 2020). "However, the previous study suggest against this because the effect of insulin on flavivirus restriction can persist even at five days after infection." (PMID 32866199, 2020). "As Tk reduces insulin signaling and lipid storage, it may be one of the reasons for the infection-related TAG decrease." (PMID 32457651, 2020). "In addition to the canonical Toll and IMD pathways, the induction of AMPs in response to infection is also regulated by the complement-like system and insulin/insulin-like growth factor signaling (IIS) in insects." (PMID 32866199, 2020). "Insulin is another peptide hormone that interferes with infections and insect immunity." (PMID 32457651, 2020). "Also, infection-induced host miRNAs in β2-adrenergic signaling and insulin signaling can block apoptosis of the infected cell." (PMID 33585554, 2020). ", infection, insulin omission, lower socioeconomic status, and lower parental education." (PMID 33143741, 2020). "Additionally, this study reported outcomes extending beyond glycemic control, finding a reduced incidence of surgical site infection in the intravenous insulin group." (PMID 31261760, 2019). "‘Insulin signaling pathway’ (n = 4) was up-regulated by infection." (PMID 31412031, 2019). "Infection reduced insulin sensitivity in the IOG when compared to that in the ICG (p < 0.05)." (PMID 31827186, 2019). "STING-mediated immunity has been previously linked to induce JAK/STAT signaling and affects nutritional homeostasis during infection implying that it may be regulated by insulin as well." (PMID 31921210, 2019). "Decreased insulin sensitivity was observed in obese animals, which was accentuated after infection." (PMID 31827186, 2019). "It has been demonstrated that ingestion of vertebrate insulin regulates whether an RNAi- or JAK/STAT-mediated response is active during infection against WNV." (PMID 31921210, 2019). "Ad-p21 infection improved glucose tolerance and insulin sensitivity in HFD-fed C57BL/6 mice." (PMID 31097688, 2019). "However, insulin treatment (DN315+i2) potentiated the effects of infection, increasing the PeLF leukocytes by 66%." (PMID 30705678, 2018).
infection (continued). "However, other studies show that some infections can activate insulin signaling, at least in Drosophila52." (PMID 29146985, 2017). "DM patient more likely require hospitalization due to glycemic imbalance as a result of infection that may require taking insulin." (PMID 28430796, 2017). "Insulin also plays an important role in the prevention against infection of bacteria and viruses by both decreasing glucose contents at the apical space of airway epithelial cells and elevating the resistance of the tight junction (barrier function) of airway epithelial cells." (PMID 28805732, 2017). "In addition, we found that infection with Ad-SIRT1 prevented NEFA-mediated insulin signaling pathway impairment." (PMID 29207650, 2017). "Some studies have shown that infections reduce insulin signaling activity." (PMID 29146985, 2017). "A high blood glucose level is an independent marker for increased incidence of infection and clinical outcome in intensive care patients, supporting the notion that insulin therapy may lower blood glucose and enhance survival." (PMID 27445441, 2016). "Infection with Ad-Klf4 resulted in morphological changes, down-regulation of mesenchymal markers, and re-expression of both epithelial and pancreatic cell markers including insulin and transcription factors specific to β-cells." (PMID 26457418, 2015). "STH infections are associated with a modest improvement of insulin sensitivity, which is not accounted for by STH effects on BMI alone." (PMID 26061042, 2015). "Furthermore, we found that infection with an increasing number of STH species incrementally enhanced insulin sensitivity." (PMID 26061042, 2015). "The increased blood pressure by insulin resistance may contribute to increased blood perfusion to the brain during starvation and infection, and to the fetus during pregnancy." (PMID 24485020, 2014). "It has been verified that long-term injection of insulin may result in lipohypertrophy, lipoatrophy and, rarely, infection." (PMID 25009591, 2014). "In addition, changes to a large subset of the protein intermediates of the insulin/mTOR pathway in the skeletal muscle were altered by infection." (PMID 23682635, 2013). "For example, reduced S6K phosphorylation after infection may result from insulin resistance driven by TAK1 via JNK." (PMID 24075010, 2013). "Moreover, patients had injection-related concerns including: pain, fear of needle, scarring from injections, lifestyle interference, infection at injection sites, forgetting to inject and insulin storage." (PMID 24282518, 2013). "Therefore, we infected MIN6 cells at a lower MOI to achieve approximately 60% infection and measured glucose stimulated insulin secretion from this mixed population by batch incubation." (PMID 22253604, 2012). "High insulin requirements may be indicative of the patient's preoperative requirements; however, it could be an early sign of infection or low cardiac output state." (PMID 23209941, 2012). "The model was adjusted by type of DM, insulin use, and presence of infection during pregnancy." (PMID 23251152, 2012). "In Drosophila, both bacterial infection and infection-independent activation of the Toll signaling pathway suppresses insulin signaling which reduces energy stores but enhances tolerance by potentially increasing investment in inducible defenses under Toll regulation." (PMID 21998579, 2011). "DKA is commonly precipitated by inadequate insulin treatment or by an acute episode of infection." (PMID 22155468, 2011). "In addition, the burden of daily injections, physiological stress, pain, inconvenience, cost, infection, inability to handle insulin, and the localized deposition of insulin leads to a local hypertrophy and fat deposition in the injection sites." (PMID 22389858, 2011).
infection (continued). "Specifically, the conserved insulin signaling pathway, which is required for C. elegans to exit the dauer stage in response to the improving environmental conditions, is also involved in the hookworm infection process." (PMID 20808816, 2010). "NIH3T3 cells were treated with insulin starting 60 min prior to infection." (PMID 20657771, 2010). "However, infection of LEDGF/p75 knockdown cells occurs only in the presence of INS or INr peptides which promote dissociation of the Rev-IN complex, formed in the infected cells." (PMID 20678206, 2010). "Other investigators have confirmed this threefold rise in insulin during an infection." (PMID 16111485, 2005). "Insulin will ordinarily rise only in response to another infection." (PMID 16111485, 2005). "An anti-infection and blood glucose management plan was established: nebulization with amphotericin B continued for the treatment of pulmonary mucormycosis, oral Cefdinir and oral Linezolid were used for bacterial infection treatment, and insulin dosage was adjusted." (PMID 41585813, 2025). "Therefore, CV-targeted interventions should prioritize the correction of underlying pathophysiological disturbances, such as infection control and stress hormone regulation, rather than relying solely on insulin-mediated stabilization." (PMID 40248149, 2025). "This suggests that during infection with wild-type M. abscessus, as with M. marinum infection of D. melanogaster, impaired insulin signaling may be an important driver of pathology and that this might be the critical difference in pathology between wild-type and ∆MAB_1132c bacteria." (PMID 39514319, 2024). "In contrast, worm clearance in humans reduces the expression of adiponectin, an adipose tissue hormone that regulates insulin sensitivity, and raises circulating insulin levels, suggesting that patent infection may be required to sustain beneficial metabolic parameters." (PMID 38277692, 2024). "Thus, our work shows how the metabolic status of M. abscessus both prior to and during an in vivo infection leads to changes in innate immune activation, which in turn leads to changes in cytokine and insulin signaling, and, ultimately, changes in pathogenicity." (PMID 39514319, 2024). "Consequently, further research is imperative to achieve a multi-tissue system composition and improved insulin secretion functionality in islet organoid, while addressing transplantation-related safety concerns, such as tumorigenicity, immune rejection, infection, and thrombosis." (PMID 38937834, 2024). "For diabetic patients, strict aseptic techniques must be followed during insulin injections: ensure a clean environment, disinfect the injection site with an alcohol swab, allow it to dry, perform the injection properly, and dispose of needles in a designated sharps container to prevent infection." (PMID 39839632, 2024). "During pathogen infection, immune system activation may modify the responsiveness of the peripheral organs to endocrine signals, resulting in altered levels of blood hormones such as insulin, which promotes the ability of the body to fight infection." (PMID 39340080, 2024). "The CRP level reached its highest on day 4 in the insulin group and became gradually lower but still remained higher than that in the other groups, indicating that patients in the insulin group might develop more severe infection and inflammation than those in the other groups." (PMID 38755442, 2024). "In addition, increased insulin resistance in skeletal muscle redirects nutrients to other organs and systems, most notably to the immune system, which is a major drain of resources during infection." (PMID 39107476, 2024). "No type of insulin therapy in-hospital was associated with lower SSI or post-discharge infection." (PMID 38063628, 2023).
infection (continued). "We thus propose that increased bacterial presence systemically and within the local pancreatic environment following infection may increase activation of islet-specific T and B cells that lead to autoimmune destruction of insulin-producing pancreatic beta cells." (PMID 36742327, 2023). "The insulin response may be related to the dryness symptoms caused by SS, while the defense response to Gram-negative bacteria may be associated with SS infection." (PMID 36091838, 2022). "However, the observed increase in gastrocnemius muscle glycogen concentration of the co-infected group at day 7 and 14 post Pb infection could be of biological importance since glucose is transported in the muscle via insulin mediated GLUT 4 transporters." (PMID 35923890, 2022). "Gradual elevation of insulin concentration in both Tz mono-infected and co-infected experimental groups coincided with a concomitant gradual elevation of muscle glycogen concentration in both Tz mono-infected and co-infected experimental groups at day 7 and 14 post Pb infection." (PMID 35923890, 2022). "Thus, metabolic dysregulation, specifically, disruptions to insulin signalling as has been shown in both F. novicida and M. luteus infections, could play a role in infection-induced activity." (PMID 36129961, 2022). "In addition, infection upregulates leptin signaling and inhibits insulin signaling." (PMID 34768822, 2021). "However, in the case of absolute or relatively insufficient insulin levels, such as fasting or infection stress, FOXO1 may be transferred from the cytoplasm and be retained in the nucleus under the action of the Jun-N-terminal kinase (JNK) signalling pathway." (PMID 34249128, 2021). "However, as his infection resolved and he improved his diet and lost weight, his blood glucose levels decreased and he was able to discontinue prandial insulin (continuing on a lower dose of basal insulin)." (PMID 33402226, 2021). "While the role of the ion transport peptide in response to infection is currently unknown, insulin signaling in insects has received considerable attention due to its role in sensing and responding to metabolic state through many channels, such as regulating olfactory sensitivity." (PMID 32911504, 2020). "In all of these cases, the insulin-to-carbohydrate ratio increases from the usual values of 0.05 to 0.2 during the normal period to higher values reaching 0.6, depending on the degree of severity of the infection incidence, type of pathogens involved, and the individual immunity." (PMID 32784178, 2020). "Moreover, acute emotional stress, other than the chronic ones, might have less influence on one’s meal appetite compared with infection incidence to skew the insulin-to-carbohydrate ratio." (PMID 32784178, 2020). "In addition, cytomegalovirus promoter-mediated expression of PPARγ in white adipose tissue due to extrahepatic infection of adenovirus particles could increase the insulin-sensitizing effects of PPARγ and reduce indirectly hepatic lipid accumulation." (PMID 32411189, 2020). "Furthermore, past infections with S. haematobium could have already imprinted their effect on insulin sensitivity, masking the influence of current infection." (PMID 32614822, 2020). "Notably, the activation of insulin signaling down-regulates the expression of immune genes, whereas the inactivation of insulin signaling induces immune genes expression and increases resistance to infection." (PMID 31505811, 2019). "The infection with Pb18 did not cause significant alterations in leukocytes present in the total blood in samples obtained 45 days after infection in both diabetic and nondiabetic groups, nor did insulin treatment significantly change this parameter." (PMID 30426021, 2018). "However, intrahippocampal insulin microinjection is invasive and may result in infection and secondary tissue damage." (PMID 29970188, 2018). "Once glucotoxicity improves and infection is controlled, insulin requirement may fall." (PMID 29270319, 2017).
infection (continued). "Therefore, in summary, it is our assertion that specific pathogenic bacteria alter the lipid metabolism of Drosophila during infection through both immune and insulin signaling pathways, which results in increased fatty-acid pheromone release by the adult insect after infection." (PMID 28814724, 2017). "Moreover, insulin release, increased after short-term infection, was significantly reduced in presence of L-798106, PGE2 receptor antagonist, NS-398, COX-2 inhibitor, and sulprostone, an EP3 agonist, demonstrating that PGE2 are responsible for the INS-1E dysfunction." (PMID 27631977, 2016). "Although tight glycaemic control after transplant may not be useful for preventing infection, a single trial has shown that modest glycaemic control using isophane insulin was able to reduce the risk of PTDM in kidney recipients." (PMID 28053992, 2016). "Likewise, infection of L6 myotubes with Ad-PIMT also suppressed insulin stimulated glucose uptake." (PMID 26468734, 2015). "Therefore, insulin resistance resulting from acute inflammatory episodes may favor nutrient poor organisms to fight against infection." (PMID 24485020, 2014). "In addition, whilst insulin failed in inducing PKCzeta phosphorylation in the muscle of TgPed/pea-15 mice injected with either vehicle or Ad-GFP, insulin-induced PKCzeta activation following Ad-D4 infection was restored to levels comparable to those of control mice." (PMID 23585839, 2013). "In addition, ORF4 mutant viruses with a reduced capacity to activate Akt showed the same phenotype, and activation of Akt by insulin was able to release this phenotype to a significant extent, thus providing further evidence for a role of Akt activation in promoting infection." (PMID 20657771, 2010). "At 48 h post-infection, the TNF and insulin signaling pathways remain continuously activated, and autophagy and ferroptosis, a novel cell death mode, are observed." (PMID 40872699, 2025). "Increased Thor transcription is indicative of repressed insulin signaling, which is consistent with the decreased phospho-AKT levels observed in ATCC 19977-infected flies late during infection, as AKT acts as an inhibitor of FoxO." (PMID 39514319, 2024). "Insulin/insulin-like growth factor 1 (IIS) and MAPK/ERK pathways are also antiviral during infection in insects." (PMID 38921161, 2024). "When the insulin-secretion-suppressing human ortholog of Lst, NMU, is supplemented to human fibroblasts expressing NMUR1, the cells show a higher viral titer after infection." (PMID 38921161, 2024). "In the presence of insulin in the culture medium, Klf2 increased the protein level of SCAP in primary hepatocytes after 48 h after Ad-ALB-Klf2 infection." (PMID 37949368, 2024). "It is believed that the increased glucose levels are due to direct infection of pancreatic beta cells by SARS-CoV-2 and decreased insulin secretion or insulin resistance in diabetic people." (PMID 38415433, 2024). "Our laboratory study found that insulin treatment in patients with T2DM significantly increased mortality and promoted infection and inflammation in different organs, contrary to common reports." (PMID 38755442, 2024). "Infection with the G. lamblia parasite can activate the AKT pathway, affecting glucose and insulin levels in the host’s body." (PMID 39201314, 2024). "Alternatively, there is a delicate balance between insulin and JAK/STAT signaling during infection necessary for a proper immune response." (PMID 38566182, 2024). "For instance, infection with G. lamblia has been shown to activate the AKT pathway, affecting glucose and insulin levels in the host." (PMID 39201314, 2024). "Serum insulin and HOMA-IR levels increased significantly after infection compared to the primary measurements." (PMID 36843827, 2023).